MIR6768 (microRNA 6768)
Synonyms: hsa-mir-6768
Gene: MicroRNA gene on chromosome 16 (2,463,967 to 2,464,038, forward strand). Ensembl gene ENSG00000274805.
Homologues: Orthologues: chimpanzee MIR6768 (100% identical).